IGKV1D-37 (immunoglobulin kappa variable 1D-37 (non-functional))
Description:
Probable non-functional open reading frame (ORF) of V region of the variable domain of immunoglobulin light chains. Non-functional ORF generally cannot participate in the synthesis of a productive immunoglobulin chain due to altered V- (D)-J or switch recombination and/or splicing site (at mRNA level) and/or conserved amino acid change (protein level). Immunoglobulins, also known as antibodies, are membrane-bound or secreted glycoproteins produced by B lymphocytes. In the recognition phase of humoral immunity, the membrane-bound immunoglobulins serve as receptors which, upon binding of a specific antigen, trigger the clonal expansion and differentiation of B lymphocytes into immunoglobulins-secreting plasma cells. Secreted immunoglobulins mediate the effector phase of humoral immunity, which results in the elimination of bound antigens. The antigen binding site is formed by the variable domain of one heavy chain, together with that of its associated light chain. Thus, each immunoglobulin has two antigen binding sites with remarkable affinity for a particular antigen. The variable domains are assembled by a process called V-(D)-J rearrangement and can then be subjected to somatic hypermutations which, after exposure to antigen and selection, allow affinity maturation for a particular antigen.
Synonyms: IGKV1D37; O4
Tractability: Antibody: UniProt places it where antibodies can reach, with medium confidence; UniProt predicts a signal peptide or a membrane-spanning region; its Gene Ontology location is reachable by antibodies, with medium confidence.
Gene: Immunoglobulin variable (V) gene on chromosome 2 (89,884,740 to 89,885,216, forward strand). Ensembl gene ENSG00000250036.
Subcellular location: Secreted; Cell membrane
Gene Ontology:
Biological process: immune response
Cellular component: extracellular region; immunoglobulin complex; plasma membrane
Homologues: Orthologues: mouse Igkv15-103 (70% identical). Paralogues in human: IGKV1-37 (100% identical), IGKV1-27 (87% identical), IGKV1-39 (87% identical), IGKV1D-39 (87% identical), IGKV1-9 (86% identical), IGKV1D-13 (85% identical), IGKV1-12 (85% identical), IGKV1-6 (85% identical), IGKV1-33 (84% identical), IGKV1D-12 (84% identical), IGKV1D-33 (84% identical), IGKV1D-16 (83% identical), and 81 more.
Diseases named in the same sentence as IGKV1D-37 in open-access papers:
IGKV1D-37 is named in the same sentence as 14 diseases in open-access papers, as found by Europe PMC text mining. Sharing a sentence is not in itself a finding about the gene and the disease.
IGKV1D-37 shares sentences with these, for which no sentence is quoted: tumor (5 papers); infection (3); central nervous system tumors (2); multiple sclerosis (2); Stroke (2); amyotrophic lateral sclerosis (1); cancer (1); cyst (1); demyelination (1); experimental autoimmune encephalomyelitis (1); glioma (1); neuroblastoma (1); neurological diseases (1); neuropathies (1).